LAG3 (lymphocyte activating 3)
Diseases named in the same sentence as LAG3 in open-access papers (continued):
Sharing a sentence is not in itself a finding about the gene and the disease.
colorectal cancer (continued). "In a large cohort of colorectal cancers, the prognostic effect differed based on the spatial location of LAG3 + tumor-infiltrating lymphocytes (TILs), and showed poor CSS in cases with high intra-tumoral LAG3 + TILs and improved CSS when LAG3 was identified in stromal immune cells." (PMID 37311986, 2023). "In d-MMR colorectal cancer, which is the archetypal example of an inflamed TME, there was also deregulated expression of numerous inhibitory immune checkpoint molecules including TIGIT, LAG3 and PD-1 which were more highly expressed in d-MMR compared to p-MMR tumors." (PMID 36781556, 2023). "Furthermore, the relationship between SIGLEC15,TIGIT,LAG3,CTLA4, PDCD1LG2 immune checkpoints and Mapk14 was only verified by correlation analysis, and we need to further explore the mechanism of Mapk14 expression in colorectal cancer in vitro and vivo experiments, such as single cell RNA sequencing." (PMID 35141222, 2022).
COVID-19 (58 papers, 2020 to 2025). A disease caused by infection with severe acute respiratory syndrome coronavirus 2. "Only one of these two phenotypes (LAG3 eQTL and COVID-19) was genetically linked around rs67706382 (PP abf of H2 = 73.6%)." (PMID 39337460, 2024). "To determine if these aberrant Tregs in patients with severe COVID-19 associate with an immune suppressive capability, we measured the level of suppressive effector molecule LAG3+ within cTregs/uTregs." (PMID 37833265, 2023). "Similar results observed that the expression of TIM-3 and LAG-3 exhaustion-associated genes was higher in SARS-CoV-2-specific CD8+ T cells from COVID-19 patients." (PMID 35126355, 2021). "Indeed, prior studies have linked high LAG-3 expression to both mild and severe COVID-19 cases and dysfunctional antiviral responses." (PMID 40977733, 2025). "Increased CD38 expression in severe COVID-19 CD8+TM was closely clustered with exhaustion-coding genes (LAG-3, TIGIT) suggesting CD38 expression is associated with metabolic reprograming, memory impairment, and cellular exhaustion of CD8+TM in the lung of COVID(+) patients." (PMID 37029220, 2023). "Clustering and shared upregulation of glycolytic enzyme encoding genes GALM, GAPDH, GPI, and ALDOA together with HIF1A, and transcripts regulating exhaustion (TIGIT and LAG3) suggested that hypoxia/anaerobic axis is associated with impaired CD8+TM function in COVID-19 BALF." (PMID 37029220, 2023). "Interestingly, patients with severe SARS-CoV-2-infection promote the expression of LAG-3 in T cells is regulated through the genes activated downstream of the IFN-I signaling." (PMID 36680187, 2023). "Finally, as an indicator of CD8+ T cell exhaustion, both PD-1 and TIM-3, CTLA-4, and LAG-3 may be associated with the disease severity of COVID-19." (PMID 36045684, 2022). "We examined plasma levels of soluble (s) CD25, TIM-3 and LAG-3, all markers of T cell activation/exhaustion, by enzyme immunoassays in 170 home-isolated and 53 hospitalized patients for up to 18 months after COVID-19 in relation to persistent symptomatology." (PMID 40519925, 2025). "Another study that analyzed the immunophenotype of blood found that activation of LAG3, an immunosuppressive factor, was responsible for immune dysregulation in COVID-19 patients." (PMID 39337460, 2024). "PD1, TIM3, and LAG3 expression was significantly increased in all cell subsets of COVID-19 patients when compared with healthy controls, except for TIM3+CD4+CD3+CD45+ (p = 0.64), TIM3+CD8+CD3+CD45+ (p = 0.41), and TIM3+CD39+CD8+CD3+CD45+ (p = 0.060)." (PMID 38793691, 2024). "Our findings revealed a causal impact of CD4+ TEM cell markers on the risk of PTB and COVID-19, providing evidence identifying two markers (GBP2 and LAG3) as prospective targets for the prevention of PTB and COVID-19 infection." (PMID 39337460, 2024). "The OR for LAG3 in COVID-19 was 1.46 (95% CI: 1.11–1.92), meaning that patients with LAG3+ CD4+ TEM cells are 1.46 times more likely to develop PTB and COVID-19 infection than patients with LAG3− CD4+ TEM cells." (PMID 39337460, 2024). "Another study suggests that the expression of T-cell immunoglobulin mucin-3 (TIM-3, also named HAVCR2) and lymphocyte-activation gene-3 (LAG3) in patients with more severe COVID-19 is much higher than that in patients with mild disease." (PMID 37932287, 2023). "Next, we were interested in evaluating the effect of COVID-19 related medications on the blood levels of IL-35+IL-10+ Bregs as well as cTregs/uTregs subsets and LAG3+cTregs/uTregs." (PMID 37833265, 2023). "Lymphocytopenia and modulation in lymphocyte balance associated with a decrease in levels of CD4+ cells, CD8+ cells, Th1, and Th2 cells and increased circulating CD4+ T cells, CD8+ T cells, Th2, PD-1, Tim-3, and LAG-3 in severe COVID-19." (PMID 36072602, 2022). "Another study observed significant elevations of soluble TIM-3 (sTIM-3) and soluble LAG-3 (sLAG-3) in severe COVID-19 patients, compared with mild disease." (PMID 35432324, 2022).
COVID-19 (continued). "We observed a significant increased level of LAG-3+CD4+ T cells among COVID-19 patients at hospitalization and again at the 6-7 month time point when compared to healthy controls." (PMID 36003367, 2022). "A high level of exhaustion markers has been reported in the severe COVID-19 patients, however, we observed elevated expression of the T cell exhaustion markers like LAG3, CTLA4, and PD-1 in the recovered individuals." (PMID 36532041, 2022). "Taken together, our scRNA-seq analysis and flow cytometry-based validation revealed the increase of an activated T cell population marked by higher expression of LAG-3 in COVID-19 patients." (PMID 35064122, 2022). "In general, upregulation of PD-1, TIM-3 and LAG-3 correlated with the disease severity in COVID-19 patients and was assigned to the lymphocyte exhaustion." (PMID 35392095, 2022). "There have been reports of increased co-inhibitory receptors, T-cell immunoglobulin mucin-3 (TIM-3) and Lymphocyte-activation gene-3 (LAG-3), in COVID-19-malaria patients." (PMID 35065613, 2022). "Of interest, a strong upregulation of LAG-3 and TIM-3 on T cells in both COVID-19 and malaria patients was linked to the co-expression of activation markers and correlated with disease course." (PMID 32983106, 2020). "For this, we compared the expression of T-bet and eomes in PD1+LAG-3+ T cells to that in PD1−LAG-3− T cells in COVID-19 and malaria." (PMID 32983106, 2020). "In COVID-19 patients we saw a similar upregulation of LAG-3 and TIM-3 on T cells of even higher frequencies on CD8+ T cells." (PMID 32983106, 2020). "In summary, the expression of activation markers (CD69, HLA-DR, CD38) on T cells was closely linked to the co-expression of inhibitory receptors (PD1, LAG-3, TIM-3) on T cells in COVID-19 and malaria patients." (PMID 32983106, 2020). "In accordance, our data show a correlation between disease severity of COVID-19 and expression of inhibitory receptors like LAG-3 and TIM-3 on T cells." (PMID 32983106, 2020). "We focused on the significant causality of GBP2 and LAG3 for PTB and COVID-19, respectively." (PMID 39337460, 2024). "Moreover, an increased gene expression level of LAG3 was detected in peripheral blood Foxp3+ Tregs15 and in lung autopsies of severely ill COVID-19 patients." (PMID 37833265, 2023). "In our study, LAG3+ Tregs correlated with a lower level of serum proinflammatory cytokines in COVID-19 patients, suggesting that immune suppressive LAG3+ Tregs might play a key role in controlling the cytokine storm associated with severe disease." (PMID 37833265, 2023). "Of note, all the genes associated with the apoptosis pathways were up-regulated in the SM group, indicating that (LAG3+CD160+CD8+)NKT cells may play a critical role in the pathogenesis of COVID-19." (PMID 35281000, 2022). "Additional inhibitory receptors such as Natural Killer group 2 member A (NKG2A), TIM-3, T cell immunoglobulin and ITIM domain (TIGIT) and Lymphocyte-activation gene 3 (LAG-3) have been hypothesized to be responsible for T-cell exhaustion in COVID-19." (PMID 35890044, 2022). "Given that the expression of MHC-II molecules (which are the ligands for LAG-3) is markedly downregulated in APCs in progressive COVID-19 patients, the disruption of LAG3-MHC-II interaction might play a critical role in COVID-19 immunopathology." (PMID 35064122, 2022). "In addition, Tim-3 and Lag-3 in particular were upregulated in the products from COVID-19 recovered individuals." (PMID 35003063, 2021). "In summary, comparing the expression of different co-inhibitory molecules in CD8+ and CD4+ T cells in COVID-19 vs. malaria, there is a transient increase of the expression of certain inhibitory receptors like LAG-3 and TIM-3 in COVID-19 in the overall context of acute immune activation." (PMID 32983106, 2020).
COVID-19 (continued). "Altogether, the simultaneous upregulation of T-bet and eomes in T cells co-expressing PD1 and LAG-3 further supports the notion that an upregulation of co-inhibitory receptors can be seen as a result of the overall immune activation during COVID-19 and acute malaria infection." (PMID 32983106, 2020). "T effector cells of COVID-19 and malaria patients showed higher frequencies of the inhibitory receptors T-cell immunoglobulin mucin-3 (TIM-3) and Lymphocyte-activation gene-3 (LAG-3) which was linked to increased activation levels and an upregulation of the transcription factors T-bet and eomes." (PMID 32983106, 2020). "In summary, comparing the expression of different co-inhibitory molecules of CD8+ and CD4+ T cells in COVID-19 vs. malaria there is a transient increase of the expression of certain inhibitory receptors like LAG-3 and TIM-3 in COVID-19 in the overall context of acute immune activation." (PMID 32983106, 2020). "Specifically, LAG3 (IVW, 3 SNPs, p = 0.0069) was found to be a risk factor along with the most notable SNP (rs67706382, p = 6.16 × 10−16), but SLFN5 (IVW, 3 SNPs, p = 0.0012) with the most notable SNP (rs67706382, p = 6.16 × 10−16) was a protective factor against COVID-19." (PMID 39337460, 2024). "Since (LAG3+CD160+ CD8+)NKT cells were also positively correlated with the disease severity, suggesting that it may function as a double edge sword, playing both protective and pathogenic roles in the pathogenesis of COVID-19." (PMID 35281000, 2022). "Elevated levels of soluble LAG-3, along with sTIM-3, s-GITR, sPD1, and sCTLA-4 were consistently higher in patients with severe and critical COVID-19, and these levels were negatively correlated with the absolute counts of CD4+ and CD8+ T cells." (PMID 39376569, 2024). "Based on CellChat analyses, monocytes communicated predominantly with CD4+ TEM cells positively expressing PTB markers (GBP2, TRAV1-2, and ODF2L) and COVID-19 markers (LAG3 and SLFN5) in both PTB and COVID-19." (PMID 39337460, 2024). "We aimed to perform in-depth immunophenotyping of major cell subsets present in human peripheral blood of COVID-19 patients and controls using PD1, TIM3, LAG3, TIGIT, and CD200R, as well as CD39, as markers for the purinergic signaling pathway." (PMID 38793691, 2024). "During some acute viral infections (e.g., flu or COVID-19), PD1 as well as other ICPMs, such as LAG3, TIM3, TIGIT, and CD200, are up-regulated." (PMID 38793691, 2024). "Inhibitory receptor molecules, such as PD-1, TIM-3, and LAG-3, are highly expressed in CD3+ T cells in peripheral blood mononuclear cells of patients with severe COVID-19 induced by acute SARS-CoV-2 infection." (PMID 36960050, 2023). "We also observed higher expression of T cell exhaustion markers, i.e., TIM-3, LAG3, CD152 or CTLA4 and CD279 or PD-1 in the recovered individuals compared to the active COVID-19 and healthy individuals." (PMID 36532041, 2022). "Some studies have shown that LAG-3 and TIM-3 are strongly upregulated on T cells in COVID-19 patients." (PMID 35432324, 2022). "In the acute phase of severe COVID-19, a considerable proportion of SARS-CoV-2-specific CD8+ T cells express TIM-3, LAG-3, TIGIT, and CTLA-4." (PMID 34413488, 2021). "Therefore, LAG3+IFNγ+CD8+ T cells may be the predominant phenotype showing exhaustion and may need to be further investigated to elucidate the pathogenic clinical severity of COVID-19." (PMID 34305939, 2021). "An exhausted CD8+ T-cell phenotype with an upregulation of IRs, such as PD-1, TIM-3, LAG-3, CTLA-4, NKG2A, and CD39, has been described in patients with COVID-19, particularly in those with severe disease." (PMID 34413488, 2021). "Expression of LAG-3 and TIM-3 on T cells in COVID-19 patients was closely related to disease course with higher levels detectable in severe patients compared to the mild patient group." (PMID 32983106, 2020).
COVID-19 (continued). "To further characterize the expression pattern of LAG-3 and TIM-3 we examined the co-expression of PD1/LAG-3 and PD1/TIM-3 on CD8+ and CD4+ T cells of COVID-19 and malaria patients compared to healthy controls." (PMID 32983106, 2020). "In COVID-19 patients we found high frequencies of single-positive PD1−LAG-3+ and PD1−TIM-3+ CD8+ and CD4+ T cells and fewer double-positive PD1+LAG-3+ and PD1+TIM-3+ T cells." (PMID 32983106, 2020). "On the same note, blockade of the inhibitory receptors LAG-3 and TIM-3 as a therapeutic strategy in COVID-19 or malaria must be critically evaluated." (PMID 32983106, 2020). "Next, we examined the expression of the inhibitory receptors PD1, TIGIT, LAG-3, TIM-3, and BTLA of T cells in COVID-19 and malaria compared to healthy controls." (PMID 32983106, 2020). "T cells of patients with COVID-19 and acute malaria showed high frequencies of the activation markers CD69 and HLA-DR/CD38 as well as high frequencies of the inhibitory receptors LAG-3 and TIM-3." (PMID 32983106, 2020). "Our data demonstrate a strong upregulation of LAG-3 and TIM-3 on T cells in COVID-19 and malaria patients across all differentiation stages." (PMID 32983106, 2020). "The upregulation of the co-inhibitory receptors LAG-3 and TIM-3 was more pronounced on CD8+ T cells in COVID-19 patients while malaria patients showed especially high expression of LAG-3 and TIM-3 on CD4+ T cells." (PMID 32983106, 2020). "Double-positive PD1+LAG-3+ and PD1+TIM-3+ cells were increased in both COVID-19 and malaria when compared with healthy donors." (PMID 32983106, 2020). "Furthermore, in COVID-19 patients, there is an observed upregulation in the expression of immune checkpoint molecules such as PD-1, CTLA-4, TIM-3, LAG-3, TIGIT, and VISTA." (PMID 39967737, 2025). "Prior findings reported that, in COVID-19, especially in severe patients, activation and exhaustion markers on the T cell surface were upregulated during acute infection, such as CD69, OX40, CD38, 4-1BB, PD-1, CTLA-4, LAG-3, TIM-3, and TIGIT." (PMID 39355257, 2024). "As CD4+ TEM cells developed, the expression of both LAG3 and SLFN5 in COVID-19 was upregulated." (PMID 39337460, 2024). "However, some studies demonstrated that these NK cells overexpressed several markers related to a dysfunctional phenotype in severe COVID-19, like CD39, PD-1, NKG2A, DUSP2, CD69, CD38, LAG-3 and TIM-3." (PMID 37311004, 2023). "The increase in blood levels of cTreg/uTreg, but not LAG3+ cTreg/uTreg subtypes, was even higher among patients with severe COVID-19 and auto-Abs to type I IFNs." (PMID 37833265, 2023). "Among the ligands of LAG-3, we observed significant decreases of MHC-II molecules on myeloid cells and B cells in progressive COVID-19 patients, which is also highlighted in our differential connectome analysis in progressive versus stable COVID-19 patients." (PMID 35064122, 2022). "Indeed, programmed cell death protein 1 (PD-1), Lymphocyte-Activation Gene 3 (LAG-3), and TIGIT expression is higher in COVID-19 patients compared to healthy controls, while DNAM-1 and NKG2D-expressing NK cells are decreased in frequency." (PMID 35844604, 2022). "Among the co-inhibitory receptors, LAG3, CTLA4, and HAVCR2 were enriched in CD8+ T cells from COVID-19 patients that eventually succumbed to the disease, but PDCD1 and TIGIT were enriched in CD8+ T cells from COVID-19 patients that eventually recovered and discharged." (PMID 36119105, 2022). "Another study also identified other cell exhaustion markers (LAG3, PDCD1 and HAVCR2) on NK cells from COVID-19 patients which could reflect that SARS-CoV-2 infection could induce these phenotypes in COVID-19 patients." (PMID 36369012, 2022). "Indeed, similar to previous reports, T cells displayed an overall exhausted phenotype, with overexpression of VISTA, TIM3, LAG3, TIGIT, and PD-1 co-inhibitory receptors in COVID-19 patient T cell populations." (PMID 33361110, 2021).
COVID-19 (continued). "To further evaluate whether the expression of LAG-3 and TIM-3 on T cells was related to the severity and disease course in COVID-19, we sub-stratified patients into a mild and a severe group." (PMID 32983106, 2020). "Additionally, we examined the frequency of CD127 expression on CD8+ T cells in COVID-19 and malaria patients in relation to the expression of the co-inhibitory receptors PD1 and LAG-3." (PMID 32983106, 2020). "This upregulation of HLA-DR/CD38 on T cells co-expressing PD1 and LAG-3 and PD1 and TIM-3 could be observed on both CD8+ and CD4+ T cells in COVID-19 and malaria patients." (PMID 32983106, 2020). "Overall, we saw a strong increase of LAG-3 and TIM-3 expression on T cells in COVID-19 and malaria." (PMID 32983106, 2020). "To see whether similar effects can be observed in COVID-19, we assessed the frequencies of the co-inhibitory receptors PD1, TIGIT, BTLA, LAG-3, and TIM-3 on CD8+ and CD4+ T cells in COVID-19 and malaria patients and compared them with healthy individuals." (PMID 32983106, 2020). "Simultaneously, alongside this, markers of exhaustion such as lymphocyte-activation gene 3 (LAG3), T cell immunoglobulin and mucin domain containing protein 3 (TIM-3), programmed cell death protein 1 (PD1), and TIGIT have been identified on NK cells in individuals diagnosed with COVID-19." (PMID 38216935, 2024). "An in vitro study performed with cells from critically ill COVID-19 patients with a predominant IFN-I response and T cells revealed two mutually antagonistic modules of ISG regulators, in which SP140 is a bidirectional regulator for LAG-3 and TIGIT under IFN-I responses." (PMID 36680187, 2023). "In addition, Tim-3+ NKT cells in COVID-19 presented a stronger capacity to secrete IFN-γ, IL-4 and IL-10 compared with healthy individuals, they also demonstrated high expression of co-inhibitory receptors such as PD-1, CTLA-4, and LAG-3." (PMID 35250975, 2022). "Interestingly, the Macro/T cell type which may be “doublets” of macrophages and T cells and expressed exhaustion markers such as LAG3 and HAVCR2, only existed in BALF of severe COVID-19." (PMID 35694714, 2022). "In adaptive cellular immune response patients with COVID-19 show a dramatic reduction in total T cells, which is negatively related to patient survival; these T cells express exhaustive signatures, such as PD-1, TIM-3, and LAG-3, all of which are immune-inhibitory factors." (PMID 33888152, 2021). "Triple-positive PD1+LAG-3+TIM-3+ T cells were nearly absent in both COVID-19 and malaria patients." (PMID 32983106, 2020). "However, the frequency of these PD1+LAG-3+TIM-3+ T cells was comparably low ranging from only 0.013–0.76% of CD8+ T cells in COVID-19 (data not shown)." (PMID 32983106, 2020).